POU3F4 (POU class 3 homeobox 4)
Description:
Probable transcription factor which exert its primary action widely during early neural development and in a very limited set of neurons in the mature brain.
Synonyms: Brain-4; Brn-4; Oct-9; OTF-9; BRN4; OTF9; DFNX2; DFN3
Gene: Protein-coding gene on chromosome X (83,508,290 to 83,512,127, forward strand). Ensembl gene ENSG00000196767.
Subcellular location: Nucleus
Subcellular location (Human Protein Atlas): Nucleoplasm
Gene-disease validity (ClinGen):
ClinGen rates the evidence that POU3F4 causes each of these diseases.
nonsyndromic genetic hearing loss (X-linked): Definitive.
Homologues: Orthologues: chimpanzee POU3F4 (100% identical), macaque POU3F4 (99% identical), mouse Pou3f4 (99% identical), rat Pou3f4 (99% identical), pig POU3F4 (98% identical), guinea pig POU3F4 (96% identical), tropical clawed frog pou3f4 (92% identical), rabbit POU3F4 (81% identical), Drosophila melanogaster vvl (53% identical), Caenorhabditis elegans ceh-18 (33% identical), Drosophila melanogaster acj6 (27% identical), Caenorhabditis elegans unc-86 (25% identical). Paralogues in human: POU3F3 (68% identical), POU3F2 (65% identical), POU3F1 (54% identical), POU2F1 (37% identical), POU2F2 (37% identical), POU2F3 (37% identical), POU5F1 (35% identical), POU5F1B (34% identical), POU1F1 (30% identical), POU4F3 (30% identical), POU4F1 (29% identical), POU6F1 (29% identical), and 5 more.